CD4 (CD4 molecule)
Diseases named in the same sentence as CD4 in open-access papers (continued):
Sharing a sentence is not in itself a finding about the gene and the disease.
tumor (continued). "TILs include T-helper cells (CD4+), cytotoxic T cells (CD8+), Foxp3+CD4+ regulatory T cells (Tregs), tumor-associated macrophages (TAMs), natural killer cells (NKCD57+), and myeloid-derived suppressor cells (MDSCs) etc." (PMID 39575251, 2024). "In the context of tumor development, a significant portion of CD4+ T cells differentiates into Tregs, enabling tumor cell immune evasion." (PMID 38317142, 2024). "In contrast, after ADT-tILC2 treatment, animals exhibited a significant increase in infiltrating CD8+, CD4+ T lymphocytes and eosinophils, specifying a robust and targeted immune response against the tumor cells." (PMID 38524132, 2024). "Regulatory T cells (Tregs) are a subset of CD4+ T cells that influence tumor immunotherapy and vaccine activation by CD4, CD25, and FOXP3 expression." (PMID 38751938, 2024). "Neoantigen-reactive CD4+ or CD8+ tumor infiltrating T lymphocytes (TILs) have rarely been detected in PDAC." (PMID 39249118, 2024). "Strong anti-tumor CD4+ and CD8+ T-cell responses were observed with enhanced secretion of IFN-γ and IL-12." (PMID 39872522, 2024). "The impact of the CD4+ T cells on tumor vascular normalization in the anti-CD47 Ab treatment was analyzed using IF double staining of CD31, α-SMA, and NG2." (PMID 38398223, 2024). "The experiment demonstrated that both CD4+ and CD8+ T lymphocytes confer resistance to naïve animals and induce tumor rejection/growth retardation, with the CD4+ T cells representing the most effective cell subtype." (PMID 39035008, 2024). "These contain seven datasets from six different studies covering tumor and lymph node samples, comprising studies with both CD4+ and CD8+ T cells (MC38_dLN, Ekiz and Xiong), only CD8+ T cells (Carmona, Singer) or only CD4+ T cells (Magen_dLN and Magen_TILs)." (PMID 38287014, 2024). "The improved recruitment of CD4+ T cells was dependent on host type I interferon signaling, consistent with the well-known role of interferon in anti-tumor response." (PMID 38858387, 2024). "Although both mCXCL10 treatment groups had a similar effect on CD8+ trafficking and attenuated tumor size, only the soluble mCXCL10 treatment resulted in a significant increase in CD4+ cells." (PMID 39553428, 2024). "In the tumor microenvironment, PD-L1+TAMs, and programmed cell death protein-1 (PD-1)+ CD4+ T cells are present, in contact with PD-L1+ tumor cells, supporting a possible role of the TAMs in the mechanism of action of checkpoint inhibitor therapy." (PMID 38285283, 2024). "Although cytokine production from CD4-positive T cells in the tumor was deemed insignificant 24 days post-tumor inoculation, CD8-positive T cells exhibited a notably increased IFN-γ and TNF-α production." (PMID 38523774, 2024). "There is increasing evidence for the comparable effectiveness of CD4+ CAR-T cells in killing target tumor cells compared to their CD8+ counterparts." (PMID 38704364, 2024). "Effective anti-tumour immunity depends on CD4+ T cells, and CD4+ T cells acquire their specificity for autologous tumours through the cross-activation of tumour antigens by autologous APCs." (PMID 38475858, 2024). "In order to examine the spatial relationship of apCAFs, tumor cells, and CD4+ effector T cells in greater detail, we leveraged the Visium ST data obtained from tumor tissue sections of patients with HNSCC, OV, BRCA, and CRC." (PMID 38903527, 2024). "The bulk of CD4+ T cells are helper T lymphocytes, which are crucial for tumor surveillance because they support CD8+ T-cell activation and proliferation as well as collaborate on antitumor actions." (PMID 38549936, 2024). "CD4 + T cells participate in immune surveillance by recognizing specific antigens on the surface of tumor cells." (PMID 38609993, 2024).
tumor (continued). "We found that the Mg‐CaCO3 exhibited rapid and stable hydrogen release capability in the weak acid TME, reduced pro‐tumor and immune suppressive factor generation of CAFs including Cxcl1 and Cxcl12, and augmented anti‐tumor immune activities of CD4+ T cells." (PMID 38757665, 2024). "Scutellaria barbata can modulate the infiltration of Treg and Th17 cells in the tumor microenvironment, reducing the number of CD4+,CD25+,Foxp3+,Treg cells and Th17 cells in tumor tissues." (PMID 39274982, 2024). "Such evidence indicates that CD8+ and CD4+ T cells are an important and effective component of the adaptive immune response to tumor cells, with recent efforts working to overcome limitations on their effectiveness." (PMID 38572312, 2024). "A higher proportion of tumor cells in dogs with AML were labeled with the anti-CD80 antibody vs antibodies against other myeloid-associated antigens, including CD4 (36%, p = 0.003), CD11b (44%), CD11c (46%), CD14 (38%, p = 0.006) and CD18 (59%, clone YFC118)." (PMID 39224452, 2024). "The sequencing of OX-40 by RNA-Seq in liver and colon cancer tissues revealed that it was overexpressed on tumor-infiltrating CD4+ T cells." (PMID 39329710, 2024). "CD4+ T cells were more prevalent in the central and peripheral tissues than in the non-tumor tissues." (PMID 38335302, 2024). "SCFAs can also inhibit histone deacytelases, which inhibit CD4+ T cell apoptosis, upregulate antitumor immune response, and suppress tumor growth." (PMID 39105827, 2024). "We found that higher CD4 level was associated with longer overall survival (OS) (P < 0.05), while CD8 and tumor-infiltrating lymphocyte (TIL) scores approached statistical significance (P = 0.051 and 0.083, respectively)." (PMID 39231924, 2024). "In fact, a higher CD4+ T cell density within the tumor was found to correlate with a poor prognosis in NMIBC." (PMID 39682686, 2024). "Regulatory T cells (Tregs) are a subset of CD4+ T cells that maintain immune homeostasis and impede tumor immune surveillance by producing the chemokines TGF-β, IL-35 and IL-10." (PMID 38792234, 2024). "TIGIT is expressed on the surface of activated CD8+ T cells, memory and regulatory CD4+ T cells, NKs, Tregs, and follicular CD4+ T cells, and is also co-expressed with PD-1 on tumor-antigen-specific T cells and TILs in various cancer patients." (PMID 38257366, 2024). "Accordingly, CD4+ T cell responses are considered indispensable for an effective anti-tumor CD8+ T cell response." (PMID 39040850, 2024). "A phase I study using an RNA-LPX vaccine targeting four tumour antigens revealed potent CD4 + and CD8 + immune responses with tumour regression in patients with unresectable melanoma." (PMID 39720956, 2024). "The CD4 depletion treatment with DMBA increased the tumor growth rates compared to DMBA only (p-value = 0.0218)." (PMID 39339897, 2024). "Analysis using the X50 T cell panel revealed that progressors had significantly higher frequencies of circulating TCF1+ CD8+ and TCF1+ CD4+ T cells (P < 0.05) than responders, which contrasts with our findings in the tumor tissue." (PMID 39190534, 2024). "Accumulating evidence has suggested that CD8+ T cells in the tumor microenvironment and systemic CD4+ T-cell immunity have a significant role in maintaining antitumor responses." (PMID 38231411, 2024). "As upstream activators of adaptive immunity, CD4+ T cells can directly activate and target tumor antigens, initiating a robust anti-tumor immune response in “cold” tumors, which include early-stage epithelial cancers and precancerous lesions." (PMID 39507526, 2024). "We confirmed that, while the recruitment of CD4+ T cells was unaffected, tumor-infiltrating CD8+ cytotoxic T cells and natural killer (NK) cells was significantly enriched by Cpt1a inhibition and 7.16.4 mAb treatment." (PMID 39097623, 2024).
tumor (continued). "Our results uncovered a robust correlation between SPC25 and the infiltration of diverse immune cell types (such as CD4 + T cells, macrophages, and T cell regulation) within multiple tumor TMEs." (PMID 38605119, 2024). "We supposed that intrapleural injection of TEVs probably promotes DC recruitment into lung tumors and subsequent presentation of tumor antigens to CD4+ and CD8+ T cells, thereby expanding these populations." (PMID 38250037, 2024). "Immunoactivation-immune cells: Apart from CD8+, evidence suggests BiTEs can also bind CD4+ helper T-cells and co-opt Tregs, leading to an expanded anti-tumour T-cell response." (PMID 39759138, 2024). "Contrary to conventional wisdom, the recent study has shown that cDC1 can activate CD4 + T cells through MHCII cross-presentation of tumor antigens." (PMID 38816871, 2024). "GSEA showed that DUSP4hi CD4 corresponded largely with previously identified tumor-infiltrating T cell clusters—including those with exhausted profiles—whereas TPT1hi CD4 corresponded more with blood/normal tissue-associated Th17 cell clusters." (PMID 38181797, 2024). "The antitumor effect of CSF-1R inhibitor pexidartinib (PLX3397) is believed to be associated with reduced CD4+ T cells and elevated CD8+ T cells, resulting in markedly depletion of macrophages and inhibition of tumor growth." (PMID 39003350, 2024). "Recent research has shown that CD4+ T cells, particularly CD4+ memory T cells, are crucial for the immunotherapy-induced tumor regression, which was consistent with the findings of our study." (PMID 39575189, 2024). "In an animal model study, it was observed that CD4+ T cells, which inhibit tumor progression, promote angiogenesis and carcinogenesis in the absence of TNFR1 or IFN‐signaling stimulation." (PMID 38287522, 2024). "Then we analyzed the pretreatment tumor tissues from 144 patients and found that female patients had a markedly higher CD4 expression level." (PMID 38899854, 2024). "The levels of macrophage M1, T-cell follicular helper, macrophage M0, and T-cell CD4 memory activation were comparatively high in the tumor samples contained in the heatmap." (PMID 38714987, 2024). "Among them, CD4 memory T cells have been reported to have the ability to recognize and attack tumor cells, thereby aiding in the regulation of tumor growth and metastatic potential." (PMID 38933262, 2024). "To elucidate which immune cells contributed to the ICB-enhanced tumor-reactivity, we performed killing assays with isolated immune subsets: CD4, CD8, γδT, NK cells, and full peripheral blood mononuclear cells (PBMC) lacking each of these populations." (PMID 38181797, 2024). "Patients with pT1-T2 tumours had significantly lower levels of CTLA-4 on CD4 cells when compared to patients with pT3-T4 lesions (adjusted p= 0.0181)." (PMID 39474426, 2024). "It has been reported that IL-21 produced by CD4+ T helper cells enhances the effector functions of CD8+ tumor-infiltrating lymphocytes (TILs) through IL-21/IL-21R signaling." (PMID 39338178, 2024). "The CD4+ T lymphocytes have the ability to interact with TAMs within the tumor microenvironment, thereby influencing the polarization of TAMs and shifting their phenotype towards a more anti-tumor M1-like state." (PMID 38426090, 2024). "IFN-γ upregulates the expression of MHC II and increases the cytotoxic effect of CD4+ CTLs on tumor cells." (PMID 38515134, 2024). "Lycopene has been shown to enhance the impact of PD-1 mAb therapy, resulting in increased tumor cell death, elevated production of anti-tumor cytokines (IL-2, IFNγ), and a higher CD4+/CD8+ ratio in the spleen." (PMID 38426097, 2024). "DC‐derived exosomes directly interact with specific cytotoxic T lymphocytes (CTL) and promote the activation of CD8+ and CD4+ T cells to inhibit tumor growth." (PMID 38783893, 2024). "S4J) and observed that depletion of CD4+ T cells abolished tumor immune control, highlighting the critical role of CD4+ T cells in PIB-mediated antitumor immunity." (PMID 39236156, 2024).
tumor (continued). "Baseline functionality, tumor burden, CD4 count, viral load, lactate dehydrogenase levels, and Light Chain Restriction protein levels were similar between the two groups, indicating a well-balanced comparison at baseline." (PMID 39957858, 2024). "Compared with mice in the other treatment groups, those treated with HCS-DOX showed increased infiltration of CD3+T and CD4+T lymphocytes into the tumor microenvironment." (PMID 38751816, 2024). "In this case GL261 themselves were acting as surrogate antigen presenting cells for their own tumor antigen for tumor specific CD4 + T cells." (PMID 39334370, 2024). "Tumor-specific CD4 + T cells showed higher expression levels of chemokine CXCL13, immune regulators FOS and JUN, and exhaustion markers TIGIT." (PMID 39033098, 2024). "Through the facilitation of the recruitment of CCR9+CXCR3+CD4+ T lymphocytes to the tumor tissue in mice, AKK bacteria can initiate an antigen-specific T cell response." (PMID 38617841, 2024). "The activation of the JAK-STAT signaling pathway in Native CD4+ T cells has been demonstrated to induce differentiation, proliferation, and suppression of anti-tumor responses in Th17 cells." (PMID 38426090, 2024). "This analysis revealed enrichment of MHC-II signaling with antigen communication from most clusters to CD4+ cells in cluster 12 (tumor cluster) only in β-M R animals compared to both β-M Control and β-M NR animals." (PMID 39711542, 2024). "After intratumor injection, mPEI/M1mt significantly potentiated anti‐PD‐L1 in combating tumor growth and metastasis by increasing the tumor infiltration and tumoricidal effects of CD4+ and CD8+ T cells." (PMID 39119940, 2024). "Both C3 and C4 were composed of tumor-infiltrating immunosuppressive regulatory CD4 T cells, as indicated by their high expression of FOXP362." (PMID 38461306, 2024). "These diverse functions are achieved through the differentiation of native CD4+ T cells upon stimulation by tumor antigens presented by antigen-presenting cells (APCs), leading to their development into effector or memory cells with specialized phenotypes." (PMID 39845973, 2024). "Cytotoxic CD4+-T lymphocytes kill tumor cells both on the fourth and sixth days after 3 h and after 20 h of incubation with tumor cells via FasL-Fas interaction, causing caspase-dependent apoptosis or RIP1 kinase-dependent necroptosis in them." (PMID 38203798, 2024). "The custom mouse panel was designed to detect T cell biomarkers CD3ε, CD4, CD8α and FoxP3 and was evaluated on murine tumor specimens with varying levels of T cell infiltration." (PMID 38605049, 2024). "The ability of CD4+ T cells to recognize tumor-specific antigens and their potential in immunotherapeutic strategies underscore the importance of integrating immune-based approaches into NSCLC treatment." (PMID 39457373, 2024). "Six tumor-infiltrating CD4+ T-cell clusters (CD4+_FOXP3, CD4+_CCR7, CD4+_LMNA, CD4+_ISG15, CD4+_CXCL13 and CD4+_MKI67) were identified after data filtering, integration, unsupervised clustering and annotation." (PMID 38383773, 2024). "In this study, we demonstrated that only the densities of CD3+CD4+Foxp3+ T cells (Tregs) on the tumor bed were significantly decreased and almost disappeared in post-NAC tissue compared with pre-NAC tissue in those with pCR." (PMID 38228697, 2024). "CD4+ T cells are an integral part of adaptiveimmunity, but their role in the immune response to a tumor remains unsettled." (PMID 39555171, 2024). "Based on the analysis in the tumor immune microenvironment, fibroblasts and CD4+ T cell, especially naive CD4+ T cells, showed their positive relationship with the risk score." (PMID 39749326, 2024). "In cases of inflammation and tumor progression, MDSCs can suppress the activity of CD4+ T cells, CD8+ T cells, and NK cells, thereby inhibiting the innate and adaptive immune responses." (PMID 39594765, 2024).
tumor (continued). "DeRogatis similarly observed in a melanoma model that PSGL-1-deficient mice exhibited augmented infiltration of CD4+ and CD8+ T cells, accompanied by elevated production of anti-tumor factors such as IFN-γ and TNF-α, resulting in delayed tumor growth." (PMID 39617949, 2024). "We showed that the constitutive deficiency of CD11chi DCs caused the almost complete inhibition of the priming of Ag-specific CD4+ T cells in LNs and TdLNs under homeostatic conditions with soluble antigenic immunization and tumor-bearing conditions." (PMID 39206204, 2024). "The phenotypic analysis of tumor-infiltrated TCR135-transduced T cells showed that TCR135-positive CD4+ and CD8+ T cells both exhibited the tissue-resident memory gene expression feature in the tumor microenvironment." (PMID 38412034, 2024). "MC38 tumors were excised at the end of the study to enumerate tumor-infiltrating CD4+ and CD8+ T-cells." (PMID 38575562, 2024). "Because hypoxia is a prominent feature in inflammation, cancer, or tumor microenvironments, studies have found that hypoxia inhibits CD4+ effector function through immunosuppression via regulatory T cells." (PMID 39551933, 2024). "In the first phase, elimination, neoantigens produced by tumor cells are recognized by the adaptive repertoire of CD4+ and CD8+ T cells." (PMID 39001453, 2024). "The anti-tumor efficacy of memory CD4 cells, CD8 cells, naive B cells, activated NK cells, and M1 macrophage cells has been validated across various cancer types." (PMID 39600313, 2024). "Briefly, conventional dendritic cells 1 (cDC1) can activate cytotoxic T cells, conventional dendritic cells 2 (cDC2) are key inducers of anti-tumor CD4 T cell responses, and monocyte-derived DCs (moDCs) can efficiently induce Treg activation and expansion." (PMID 38577107, 2024). "documented the emergence of significant tumor immune mobilization mediated by CD4 and CD8+ T lymphocytes following the initiation of Pembrolizumab in their patient, resulting in near-complete response of their MPM, while maintaining a negative PD-L1 status." (PMID 39091916, 2024). "Nevertheless, the unique role of CD4+ T cells in optimizing anti-tumor immunity is becoming increasingly well-established." (PMID 39483483, 2024). "Another study showed a different outcome, the elevated density of CD4+ or CD8+ TILs in patients with high CTLA-4 expression on interstitial lymphocytes or tumor cells, the superior outcomes in the group of high CTLA-4 expression level." (PMID 39845973, 2024). "FOXO1 overexpression enhanced CAR T cell efficacy as indicated by a significant decrease in tumour mass, which was associated with a significant increase in the number of CD8+ and CD4+ CAR T cells in the blood and spleen of treated mice." (PMID 38600376, 2024). "In our study, we found that CXCL13 was specifically upregulated in tumor-infiltrated TCR135-positive CD4+ T cells, while ZNF683 was specifically upregulated in tumor-infiltrated TCR135-positive CD8+ T cells." (PMID 38412034, 2024). "Treatment with this monoclonal antibody decreased levels of GZMB/CCL5 expressed per CD4+ T cell harvested from T3 or F244 tumour-bearing mice." (PMID 39048822, 2024). "Previous studies have demonstrated that low CD4 + /CD8 + ratio is a crucial indicator of the severity and poor prognosis of malignant tumors, with a lower ratio indicating a higher risk of tumor metastasis and recurrence." (PMID 38834662, 2024). "In PM1, CD226 was expressed in CD27+ CD4+ and CD4+ Memory subpopulations, and corresponding ligands in tumor cells were TIGB2, NECTIN2 and PVR." (PMID 38528036, 2024). "A higher proportion of cytotoxic CD8+ T cells was observed in CR705Parp7KO tumours relative to CD4+ and TCRγδ T cells." (PMID 39867896, 2024). "In contrast, those from CD4+ T cell–depleted mice exhibited robust tumor cell elimination much like the splenocytes from LPP-CT26–immunized mice that received immunoglobulin G injections." (PMID 39392882, 2024).